FOXQ1 (forkhead box Q1)
Diseases named in the same sentence as FOXQ1 in open-access papers (continued):
Sharing a sentence is not in itself a finding about the gene and the disease.
tumor (continued). "The expression profile of FOXQ1 in pan-cancer is unclear, the intrinsic correlation of structural variation with FOXQ1 expression is unknown, and whether its effect on tumor progression is related to changes in immune function remains to be elucidated." (PMID 36118871, 2022). "Our results show that FOXQ1 may play a role in mediating tumor immunity, which has major usefulness in guiding the exploitation of new anticancer immune therapeutic targets." (PMID 36118871, 2022). "FOXQ1 alters the tumor microenvironment (TME) by regulating versican V1." (PMID 36118871, 2022). "Tumor-associated macrophages, major components of tumor microenvironment associated with cancer metastasis, induce EMT for colorectal cancer migration and circulating tumor cell-mediated metastasis via JAK2/STAT3/miR-506-3p/FoxQ1 axis activated by IL-6." (PMID 34660694, 2021). "FOXQ1 is a potent activator of Wnt/β-catenin signaling, and thus FOXQ1 induction may trigger a positive feedback loop that promotes tumor progression in some cancers, including CRC." (PMID 34298659, 2021). "Foxq1 was shown to be expressed in several tumor types and may facilitate tumor initiation, proliferation, metastasis, and invasion; however, its function in PDAC remains unclear." (PMID 35141228, 2021). "Based on our findings, FOXQ1 may serve as a therapeutic target for CRC treatment by inhibiting tumor angiogenesis and reducing macrophage recruitment." (PMID 33330033, 2020). "Furthermore, the morphological features of CRC were verified by H&E staining of xenograft tumor tissues, and immunostaining of FOXQ1 in dissected tumor tissues confirmed the reduction of FOXQ1 in DLD1-shFOXQ1 (P<0.01)." (PMID 33330033, 2020). "Furthermore, clinically relevant genes that are associated with tumor growth such as VIM, ITGB1, FOXQ1, FN1, MSN, CXCL and TMPRSS4 were also downregulated." (PMID 32784836, 2020). "Finally, Kaplan-Meier survival analysis was performed to further validate the role of FOXQ1 in promoting tumor angiogenesis and TME modification." (PMID 33330033, 2020). "Additionally, the expression of FOXQ1 protein in tumour tissues from miR-4319 knockdown-injected mice was significantly higher than that in control mice." (PMID 31853229, 2019). "In agreement with the role of FGFR1 in promoting cell proliferation and carcinogenesis, a number of iFGFR1-upregulated genes are cancer-driving genes such as ETS1, PIM1, NRG1, MMP1, and FOXQ1, while some iFGFR1-downregulated genes are tumor suppressors such as NR4A1 and GDF15." (PMID 30111373, 2018). "FOXQ1 is overexpressed in epithelial and stromal tumor compartments along with other EMT genes." (PMID 29258163, 2017). "Therefore, our study uncovers a role and mechanism of FOXQ1 in the regulation of cell senescence, offering new insights on the balance between cell senescence and tumor development." (PMID 28726780, 2017). "For example, overexpression of FOXQ1 has been shown to increase CRC tumour growth in mice." (PMID 28169291, 2017). "Ectopic expression of FOXQ1 promoted an anti-apoptotic effect and enhanced tumor growth." (PMID 29258163, 2017). "Authors suggested that tumor suppressor role of miR-506 was mediated by FOXQ1 downregulation." (PMID 28405738, 2017). "Our in vitro and in vivo findings shed light on how FoxQ1 promotes tumor progression in NSCLC." (PMID 25356753, 2014). "Moreover, miR-422a exerts its tumor suppressive effects by inhibiting the expression of FOXQ1." (PMID 40176914, 2025). "In addition, TAMs modulate tumor metastasis by regulating the EMT process through STAT/miR-506-3p/FoxQ1 signaling and TAT/miR-506-3p/FoxQ1 pathway and promote extracellular matrix degradation via secreting matrix metalloproteinases and C-C motif chemokine ligand 18 (CCL18)." (PMID 36845095, 2023). "In addition, studies have shown that FOXQ1 protein promotes tumor angiogenesis." (PMID 36118871, 2022). "Therefore, we predicted that FOXQ1 was able to regulate tumor progression via these pathways." (PMID 36118871, 2022).
tumor (continued). "In addition, the xenografts grew rapidly and became heavier in mice injected with CRC cells overexpressing β-catenin as compared with mice injected with NC CRC cells; and the tumor-promoting effects of β-catenin overexpression alone was repressed when combined with FOXQ1 knockdown." (PMID 35183223, 2022). "However, despite involvement of FoxQ1 in migration, invasion and proliferation of tumor cells, its functional role in monocytes/macrophages and association with human pathologies other than cancer remained unknown." (PMID 29203829, 2017). "Because of the diverse roles of FoxQ1 in cancer development, including regulation of tumor cell proliferation, invasion, angiogenesis, and anti-apoptosis, a better understanding of FoxQ1 signaling and function may help identify novel and effective targets for cancer therapy." (PMID 23383267, 2013). "Three genes (PRSS21, FOXQ1, and MMP7) formed a highly upregulated cluster, with a fold increase greater than 220 in tumor tissues." (PMID 41465326, 2025). "Three genes: PRSS21, FOXQ1, and MMP7, formed a highly upregulated cluster exhibiting a fold increase greater than 220-fold in tumor tissues (Median (Range) = 1273 (228–1598) fold increase)." (PMID 41465326, 2025). "LINC00543 remolds the tumor-microenvironment in CRC and enhances the epithelial-mesenchymal transition (EMT) of CRC cells through the pre-miR-506-3p/FOXQ1 axis." (PMID 41347087, 2025). "miR-342 is a tumor suppressive miRNA targeting the regulation of FOXQ1 biological function and thus affecting CRC development and clarified FOXQ1 as a valuable prognostic marker for CRC." (PMID 41347087, 2025). "HLF accelerates tumor growth and metastasis via modulation of frizzled-4 (FZD4) and forkhead box Q1 (FOXQ1)." (PMID 38545555, 2024). "And the results denoted that PC tissues showed higher FOXQ1 and LDHA protein levels than that in the nearby non-tumor tissues." (PMID 37875474, 2023). "The most important finding in this study is that the expression levels of the fibroblast biomarkers FOXQ1, MMP11 and THBS2 are significantly elevated in both primary tumor tissue and H&E(+)LNs of CC patients." (PMID 38156105, 2023). "Knockdown of FOXQ1 blocked the FGFR1 signaling-stimulated BC cell proliferation, colony formation, and xenograft tumor growth." (PMID 36778115, 2023). "Immunomorphometry analyses revealed that FOXQ1-, MMP11- and THBS2-positive cells were present at significantly higher numbers in the CC tumor region than in normal colon epithelium (P < 0.0001)." (PMID 38156105, 2023). "Potential correlation between levels of the fibroblast biomarkers FOXQ1, MMP11 and THBS2 in primary tumor tissue was investigated." (PMID 38156105, 2023). "CAFs are found to induce FOXQ1 expression and FOXQ1/N-myc downstream-regulated gene 1 (NDRG1) axis is activated in tumor cells, which contributes to HCC initiation." (PMID 37007125, 2023). "UroAmplitude identified TERT, PLEKHS1, FOXQ1, KMT2C, and ERBB2 somatic events in urine collected prior to resection of an HG T1 multifocal tumor." (PMID 36233691, 2022). "The upregulation of FoxQ1 accelerates the induction of EMT in tumor cells and promotes tumor metastasis and invasion." (PMID 36611857, 2022). "Knockdown of FOXQ1 expression suppresses the angiogenic capacity of tumor cells by regulating VEGF, which is an activator of angiogenesis that is secreted by tumor cells." (PMID 36118871, 2022). "Our data has repeatedly identified FOXQ1 bound to intact MLL core complex as shown through FOXQ1 TAP-MS in HEK293 cells and FOXQ1 or RbBP5 IP from the mammary cell model (HMLE/FOXQ1), TNBC cell lines, and tumor samples." (PMID 36319643, 2022). "Direct interaction of FOXQ1 and RbBP5 was further validated in TNBC cell lines and various human tumor samples, including TNBC." (PMID 36319643, 2022).
tumor (continued). "We initially found a significant correlation of FOXQ1 expression with the TMB and MSI in different tumors, and we predicted that it has the potential to be a tumor immunotherapy target." (PMID 36118871, 2022). "We investigated in vivo the relationship between Foxq1, NPC growth and VM formation using a subcutaneous BALB/c nude mice xenograft tumor model (n = 6/group)." (PMID 33875643, 2021). "Indeed, studies have found that TAMs can induce the expression of FOXO1 protein in gastric cancer cells, thus promoting EMT, invasion, and metastasis of tumor cells, which indicates that FOXQ1 repression in tumor cells may be the key to inhibiting tumor metastasis." (PMID 33224886, 2020). "FoxQ1 inhibition via miR-506-3p and subsequent CCL2 upregulation can promote circulating tumor cell (CTC)-mediated tumor metastasis in CRC patients." (PMID 31887997, 2019). "As a tumour suppressor, miR-4319 directly targets the 3-UTR of FOXQ1 and controls its expression in HCC." (PMID 31853229, 2019). "FOXQ1 overexpression was correlated with high histological grade (Edmondson-Steiner grade III + IV; P=0.029), late tumour stage (TNM stage III + IV; P=0.027) and venous invasion (P=0.032)." (PMID 31853229, 2019). "FOXQ1 overexpression has been seen to play a relevant role in enhancing CRC tumorigenicity, tumour growth and migration/invasion of tumour cells by mainly acting on WNT and TGF-B molecular pathways." (PMID 30621735, 2019). "In NPC, our previous studies showed that both miR-9 and miR-124 functioned as tumor suppressors by targeting chemokine receptor-4 (CXCR4) and forkhead box Q1 (FOXQ1), respectively." (PMID 29581984, 2018). "Taken together, these findings uncover a previously unidentified role of FOXQ1 regulating SASP and tumor development at same time." (PMID 28726780, 2017). "We investigated the link between FoxQ1 and EMT at vitro cells and in vivo tissues levels, in keeping with our previous study on tumor TMA." (PMID 25356753, 2014). "Our findings describing the interplay between FoxQ1 and EMT provide significant contributions to the exploration of EMT in tumor progression and invasion." (PMID 25356753, 2014). "Growth curves showed that the tumor volume in SPC-A-1-FoxQ1 and NCI-H1395-FoxQ1 cells silenced for FoxQ1 expression was much lower than that in corresponding control and normal control mice." (PMID 25356753, 2014). "Our results demonstrate that miR-124 functions as a tumor-suppressive microRNA in NPC, and that its suppressive effects are mediated chiefly by repressing Foxq1 expression." (PMID 25098939, 2014). "Notable examples, such as FOXQ1, MAST2, and CDH4, were found to play a role in hair follicle development and human cancer, signal transduction, and tumor repression, respectively." (PMID 23349834, 2013). "Overall comparison in different tumor tissues of the expO data, the NCI60 cell line panel and a panel of 967 cell lines revealed that FOXQ1 median expression was highest in CRC compared to all other solid tumors." (PMID 23555880, 2013). "High FoxQ1 expression was detected in 82/103 (50.49%) of NSCLC tissues and was in 38 (20.39%) of the adjacent matched tumour tissues." (PMID 22761930, 2012). "Multiple studies reported silencing of FOXQ1 by various miRNAs in different types of cancer, and collectively suggest that post-transcriptional inhibition of FOXQ1 may prevent EMT and tumour progression." (PMID 39777582, 2025). "Furthermore, miR‐133a‐3p downregulation counteracted the tumor‐suppressive effects of RP9P knockdown, highlighting the RP9P/miR‐133a‐3p/FOXQ1 axis as a critical pathway in CRC progression." (PMID 40556338, 2025).
tumor (continued). "The PARP inhibitor niraparib significantly suppressed tumor growth in a mouse xenograft model of FOXQ1-expressing OC, suggesting that PARP inhibition may offer therapeutic benefit by targeting FOXQ1." (PMID 40746724, 2025). "When interacting with FOXQ1, these proteins can convert each other into either transcription activators or repressors, thereby inducing or suppressing the expression of N-cadherin (CDH2 gene), a key regulator of tumor invasion and metastasis." (PMID 41347087, 2025). "However, the DNA recognition motif of FOXQ1 is highly similar to most of the other FOX family members, including known tumour suppressors such as FOXF and FOXO proteins." (PMID 39777582, 2025). "The FOXQ1/NDRG1 axis promotes the initiation of HCC by modulating the crosstalk between CAFs and tumor cells, which forms a circular reinforcement loop to attract HSCs and encourage tumor proliferation." (PMID 40755769, 2025). "Interestingly, these authors observed a feed-back loop mediated by the FOXQ1 target gene NDRG1 that induced various chemokines including CCL26, which promoted the migration of additional CAFs to the site of the tumour." (PMID 39777582, 2025). "Since FOXQ1 and THBS2 were ectopically expressed in CC tumor cells it was of interest to compare their expression with other ectopically expressed biomarkers like the chemokines CXCL16 and CXCL17 particularly since these two chemokines were associated with bad prognosis." (PMID 38156105, 2023). "Furthermore, mechanistic studies indicated that FOXQ1 promotes LDHA transcription, and thus modulates aerobic glycolysis to enhance PC cell proliferation, tumor stemness, invasion, and metastasis by increasing LDHA expression." (PMID 37875474, 2023). "The increased expression of FOXQ1, and THBS2 is explained by ectopic expression in CC-tumor cells." (PMID 38156105, 2023). "In addition, the tumor sphere formation ability of HCT116R and HT29R cells was enhanced in response to SIRT1 overexpression and reduced in response to FOXQ1 knockdown." (PMID 35183223, 2022). "Moreover, genetic disruption of the FOXQ1-RbBP5 interaction or pharmacologic targeting of KMT2/MLL recruitment inhibits FOXQ1-dependent gene expression, EMT, and in vivo tumor progression." (PMID 36319643, 2022). "al. also found overexpressed FOXQ1 in CRC samples and further revealed that FOXQ1 could enhance tumorigenicity and tumor growth via its angiogenic and antiapoptotic functions." (PMID 35183223, 2022). "Likewise, the FOXQ1/NDRG1 axis was shown to exacerbate HCC initiation via enhancing cross talk between fibroblasts and tumor cells, and FOXO1 was reported to contribute to HCC through a different mode of action." (PMID 31615920, 2019). "Considering that the DNA recognition motifs of FOXQ1 and FOXF2 are virtually identical, this study provides an interesting example of the critical role of transcription co-factors in shaping the function of transcription factors as oncogenes or tumour suppressors." (PMID 39777582, 2025). "Notably, knockdown of FOXQ1 significantly potentiated tumor growth control by irradiation treatment, but did not affect tumor growth without irradiation." (PMID 38062011, 2023). "The mRNA expression of tumor stem cell markers (CD133, SOX2 and OCT4) in the CRC xenograft tissues of mice was then found to be up-regulated in the presence of β-catenin overexpression alone, and the up-regulation was reversed when β-catenin overexpression was combined with FOXQ1 knockdown." (PMID 35183223, 2022). "Although the relationship between Foxq1 and VM has not been reported, other studies have shown that Foxq1 promotes tumor metastasis by promoting epithelial-mesenchymal transition (EMT) in a variety of tumors, including gastric, lung, colorectal, breast, and bladder cancers." (PMID 33875643, 2021).
tumor (continued). "Cells in which the expression of FoxQ1 was silenced (SPC-A-1-FoxQ1 and NCI-H1395-FoxQ1), their corresponding control cells (SPC-A-1-scr and NCI-H1395-scr) and normal control cells were subcutaneously injected into the bilateral flank, and tumor size was measured and recorded every three days." (PMID 25356753, 2014). "Although the exact mechanisms of FoxQ1's tumorigenic effects in NSCLC have not been described fully in our present investigation, the molecular basis for the association between FoxQ1 and EMT are well understood in tumor." (PMID 22761930, 2012). "The role of Twist1-induced CCL2 in angiogenesis has been demonstrated, which raises the possibility that FOXQ1 may induce angiogenesis in CRC by inducing Twist1; however, a role for FOXQ1 in inducing tumor angiogenesis and TME modification in CRC has not been evaluated." (PMID 33330033, 2020). "Thus, we sought to not only confirm the differential expression of RIPK2, FOXQ1, KRT23 and EPHX4 in the investigated tumor samples, but also examine whether the differential epigenetic marking of the genes was, indeed, specific for tumor cells and not from stromal contamination." (PMID 31404997, 2019). "Hence, downregulation of FoxQ1 might increase the sensitivity of NSCLC cells to chemotherapeutic reagents, and may be related to our above result demonstrating that decreasing FoxQ1 expression could induce tumor cell apoptosis." (PMID 25356753, 2014). "One study judged FOXQ1 not to be a useful prognostic marker in CRC when it was investigated for predicting outcome, thus, if elevated in the primary CRC tumor there was a 5-years survival in the high group of 52% compared to 66% in the low group (P=0.11)." (PMID 38156105, 2023). "We conclude that CC tumor cells show ectopic expression of FOXQ1 and THBS2 possibly making these tumor cells independent of fibroblast cell support." (PMID 38156105, 2023). "Taken together, these observations suggest that FOXQ1 contributes to the treatment resistance of cancer cells not only indirectly via the induction of EMT, but also through the direct control of mechanisms that make tumour cells resistant to different types of treatments." (PMID 39777582, 2025). "The fact that FOXQ1 and THBS2 are not expressed or expressed at very low levels in immune cells should make these two markers suitable for LN analysis, which has proved to be superior to analysis of primary tumor for prediction of outcome by molecular techniques." (PMID 38156105, 2023).